SMO (smoothened, frizzled class receptor)
Diseases named in the same sentence as SMO in open-access papers (continued):
Sharing a sentence is not in itself a finding about the gene and the disease.
glioma (continued). "On the other hand SHH, SMO, GLI1, GLI2, GLI3_A (core Hedgehog pathway molecules) were activating the other proteins in both normal as well as Glioma scenarios." (PMID 23935937, 2013). "The role of few important proteins such as PTCH1, SMO, GLI etc., in this pathway has already been identified to be responsible for various types of cancers, such as Glioma, Colon and Pancreatic." (PMID 23935937, 2013). "If it does exist, it appears to dissociate at the distal tip, based on our immunolabeling of distal tip buds that appear strongly SMO- but weakly ARL13B-labeled, which would suggest other factors are present in the glioma ciliary tip to promote this dissociation." (PMID 37830570, 2023). "Gliomas with BRAF gains commonly had concomitant gains in MET, SMO, EZH2, and CDK6 (p < 0.001 each), along with other genes on 7q, which may reflect larger chromosomal duplications." (PMID 36854806, 2023). "Our goal was to try and distinguish whether ARL13B inside or outside of glioma cilia drives the ciliary changes in SMO, and whether ARL13B drives increases in activated ciliary SMO." (PMID 37830570, 2023). "Because gliomas are notoriously heterogeneous tumors, future studies should determine if glioma stem cells with ARL13B+ cilia display different capacities for enriching or activating SMO and GLI." (PMID 37830570, 2023). "Collectively, these data suggest that increasing functional ARL13B inside the cilium leads to the lengthening of glioma cilia and a distal tip accumulation of SMO that is independent of exogenous SHH exposure." (PMID 37830570, 2023). "Collectively, our data suggest that factors increasing ARL13B expression in glioma cells may promote both changes in ciliary membrane characteristics and IFT proteins, leading to the accumulation of drug-resistant SMO and GLI." (PMID 37830570, 2023). "Thus, how these findings relate to glioma cells and whether the relationship between ARL13B and SMO is SHH-dependent remains unclear." (PMID 37830570, 2023). "Glioma cells overexpressing ARL13B also display reduced ciliary intraflagellar transport 88 (IFT88), suggesting that altered retrograde transport could further promote SMO/GLI accumulation." (PMID 37830570, 2023). "Furthermore, the combined using of sh-circSMO742 and SMO antagonist, such as Sonidegib, Cyclopamine, SNAT-1, and MK-4101 on the treatment of glioma could be further investigated." (PMID 31895689, 2019). "Moreover, we found that, in response to SMO agonist purmorphamine treatment, the activity of GLI1 was only slightly increased in SW 1088 glioma cells, which displays low NUSAP1 expression, but significantly increased in U-87 MG glioma cells, which exhibits high NUSAP1 expression." (PMID 28899410, 2017). "However, we do not know whether the ARL13B-mediated changes in the glioma cilia length or the SMO distribution are attributable to ARL13B’s ciliary or cellular role." (PMID 37830570, 2023). "However, the regulation mechanism of SMO in glioma is still not clear." (PMID 31895689, 2019). "It is possible that even in the absence of the SHH ligand, glioma cells that fail to properly maintain specific intracellular levels of Arl13b may undergo abnormal activation of ciliary signaling through the upregulation of SMO into their cilium." (PMID 30410731, 2018). "However, glioma cell lines whose cilia overexpress WT but not guanine exchange factor-deficient ARL13B, display reduced INPP5e, a ciliary membrane component whose depletion may favor SMO/GLI2 enrichment." (PMID 37830570, 2023). "Alternatively, in glioma, ARL13B does not bind or promote SMO ciliary localization." (PMID 37830570, 2023). "The relationship between ARL13B, SMO, and GLI2 may be independent of SHH expression in glioma." (PMID 37830570, 2023).
glioma (continued). "Similarly, we reported that Arl13b overexpression promotes SMO localization to GBM cilia in the absence of SHH, and that high levels of ARL13B and SMO expression in the tumors of glioma and gastric tumor patients was positively correlated with shortened post-diagnosis survival in these patients." (PMID 30842728, 2019).
melanoma (29 papers, 2013 to 2026). A malignant, usually aggressive tumor composed of atypical, neoplastic melanocytes. "One of these studies pointed out that primary melanoma cell lines with BRAF mutation are more sensitive to SMO inhibitor, sonidegib, than BRAF wild-type cells." (PMID 36139698, 2022). "Here we report, for the first time to our knowledge, a clinical case where a melanoma patient harboring the SMO p.Gln216Arg mutation has been treated with imiquimod, showing a complete and durable response." (PMID 33799349, 2021). "To better explain this outstanding response to the treatment, we transfected a melanoma cell line (MeWo) with the SMO p.Gln216Arg mutation in order to evaluate its role in response to the imiquimod treatment." (PMID 33799349, 2021). "Inhibition of the Hh pathway seems to be a promising target in melanoma; it is reported that an elevated SMO expression is associated with a shorter survival of melanoma patients, while higher GLI3 (Hh pathway repressor) expression is related to better survival." (PMID 38399442, 2024). "However, analyzing our institutional database containing NGS data from 1878 melanoma specimens, we found only three SMO mutations corresponding to about 0.16% of patients (manuscript in preparation), suggesting that genetic alterations in this gene are rare in untreated patients." (PMID 41596411, 2026). "In this study, we employed high-throughput proteomic arrays, including 58 proteins involved in immunity, to assess the impact of SMO inhibition on key inflammatory mediators in melanoma cells." (PMID 41596411, 2026). "The most relevant effect of Hh inhibition by SMO inhibitors consists of the dose-dependent reduced proliferation of melanoma cells, which culminates in apoptosis at higher concentrations." (PMID 41596411, 2026). "The increased release of SHH following SMO inhibition suggests a finely tuned regulatory mechanism within this signaling pathway, underscoring its significance in melanoma biology." (PMID 41596411, 2026). "This inhibition of SMO and Gli1 by Itraconazole not only reduces melanoma cell proliferation but also induces apoptosis." (PMID 39917616, 2025). "led to the development of novel SMO inhibitors based on acylguanidine or acylthiourea scaffolds, which specifically target SMO in melanoma cells, thereby reducing Gli1 expression, inducing DNA damage and apoptosis, and inhibiting the self-renewal of MSCs." (PMID 39611156, 2024). "For example, pancreatic-derived CAFs show elevated levels of SMO and GLI1 expression, whilst melanoma-associated CAFs exhibit reduced extracellular matrix production and paracrine signalling when β-catenin is inhibited." (PMID 35159339, 2022). "For example, the potent acylguanidine derivative targeting SMO (MRT-92) has shown good results in decreasing human melanoma xenograft growth in vivo." (PMID 33958721, 2021). "Here we show that co-targeting BRD4 and SMO elicits a significant antitumor activity in melanoma, including a drastic reduction of 2D and 3D melanoma cell growth and melanoma stem cell-like self-renewal." (PMID 33958721, 2021). "We also tested the effects of the combination of ERK5 (XMD8-92) or MEK5 (BIX02189) inhibitors with GLI (GANT61) or SMO (MRT-92) inhibitors on the viability of melanoma cells, used at low (IC10) concentrations." (PMID 34681917, 2021). "Lastly, inhibition of HH-GLI pathway by the SMO inhibitor NVP-LDE225 is associated to the inhibition of cell growth and induction of apoptosis in human melanoma cell lines." (PMID 34445078, 2021). "On the contrary, treatment of SMO-depleted melanoma cells (LV-shSMO) with both compounds showed a minor effect only at 1 μM in both cell types." (PMID 29396391, 2018). "To confirm the specificity of 1 and 2 for SMO, we silenced it in melanoma cells using a short hairpin RNA specific for SMO40 and we treated them with increasing concentrations of either compounds." (PMID 29396391, 2018).
melanoma (continued). "Along with others, we previously showed that inhibition of SMO reduces growth of human melanoma cell lines in vitro and in vivo." (PMID 29396391, 2018). "Our data highlight a novel route for cell death induction by SMO inhibitors and support their use in therapeutic approaches for melanoma and, possibly, other types of cancer with active HH signaling." (PMID 29396391, 2018). "Studies revealed that over 40% of the melanoma cell lines examined harbored significantly elevated levels of the hedgehog pathway mediators SMO, GLI2, and PTCH1 compared to melanocytes (p < 0.05)." (PMID 24287465, 2013). "Smoothened (SMO) inhibitor, cyclopamine decreases the ability of melanoma cells to form lung metastasis." (PMID 23342114, 2013). "Previous studies reported a possible anti-migratory activity of SMO inhibitors on melanoma cells." (PMID 41596411, 2026). "Pharmacological modulation of Hh impacts the major critical features of cancer cells: the proliferation, the migration, and the crosstalk with components of proximal stroma, supporting the use of SMO inhibitors such as sonidegib and vismodegib for melanoma therapy." (PMID 41596411, 2026). "Development of new small molecules could be crucial, as evidence of drug resistance is arising in some types of melanoma as well as in other Hh-related tumours upon treatment with SMO antagonists." (PMID 38399442, 2024). "We have previously demonstrated that melanoma migration and invasion can be impaired by siRNA targeting Hh pathway components: siRNA treatment targeting SMO and GLI1 was effective and proved to reduce migration and invasion in two different melanoma cell lines, SK-MEL-28 and A375." (PMID 38399442, 2024). "The isobologram summarizes the combination index (CI) at the IC50 when the SMO inhibitor MRT-92 and the BRD4-degrader MZ1 were combined, showing a moderate synergistic anti-proliferative effect (CI < 1) in melanoma cells independently of their BRAF, NRAS, and NF1 mutational status." (PMID 33958721, 2021). "Combination of MZ1, a potent BRD4 degrader designed using the Proteolysis Targeted Chimeras (PROTACs) technology, with the SMO inhibitor MRT-92 yields a synergistic reduction of melanoma cell growth in vitro and in vivo, providing a rationale for a novel therapeutic approach in melanoma." (PMID 33958721, 2021). "Preclinical studies have shown the efficacy of SMO inhibition in reducing tumor burden in melanoma." (PMID 33958721, 2021). "Further, we performed in vitro studies of the effects of flavonolignans on mechanisms including the targets of the corresponding drugs—BRAF V600E kinase activity, the viability of A-375 human melanoma cells (with BRAF V600E mutation), and Hedgehog (HH) signaling pathway, including SMO." (PMID 32380762, 2020). "Finally, the NGS analysis identified genomic amplification of the smoothened homolog (SMO) gene in a melanoma patient and thereby SMO inhibitors (sonidegib and vismodegib) were suggested as a treatment of choice for that cancer." (PMID 32411592, 2020). "Hence, concurrent use of HDAC- and SMO- inhibitors holds a promising strategy to target melanoma, as predicted by romidepsin and vismodegib combination." (PMID 33262326, 2020). "Thus, we tested the ability of 1 and 2 to suppress proliferation of human melanoma cells compared with the SMO antagonist LDE-225." (PMID 29396391, 2018). "We profiled a panel of human melanoma cell lines and control melanocytes for altered expression of hedgehog pathway members and determined the consequences of both genetic and pharmacological inhibition of the hedgehog pathway activator Smoothened (SMO) in melanoma, both in vitro and in vivo." (PMID 24287465, 2013). "In summary, our pre-clinical studies support SMO as a therapeutic target in melanoma and offer insights into the clinical potential of this new treatment strategy both as a single agent and in combination with other targeted agents in metastatic melanoma patients." (PMID 24287465, 2013).
melanoma (continued). "Moreover, the concentration of SHH dose-dependently augmented in the presence of the SMO antagonist, arguing for an intrinsic tight modulation of the signaling by melanoma cells and the endeavor to counteract its suppression imposed by pharmacological treatment." (PMID 41596411, 2026). "Indeed, a SMO inhibitor cyclopamine significantly diminished the activity of the survivin promoter in many cell lines to various extents (30–70%), as exemplified in three melanoma cell lines." (PMID 26775700, 2016). "Based on the responses to NVP-LDE-225 in our melanoma cell line panel, it appears that a subset of patients whose tumors harbor either V600E B-RAF mutations or N-RAS mutation may benefit most from inhibition of SMO." (PMID 24287465, 2013). "We have previously demonstrated that CAXII is downregulated by SMO and GLI1 siRNA, resulting in melanoma migration and invasion impairment." (PMID 38399442, 2024). "Inhibition of the Hedgehog pathway, particularly targeting the activator smoothened (SMO) using small interfering RNA (siRNA) and the small molecule inhibitor NVP-LDE-225, has been effective in curbing melanoma growth in vitro." (PMID 39611156, 2024). "By using a genetic approach based on the transient silencing (siRNA) of SMO, GLI1, and CAXII, we showed that melanoma cell migration and invasion were affected by CAXII and the Hh pathway." (PMID 36230699, 2022). "We demonstrated that the inhibition of both SMO and GLI1 decreased CAXII expression and impaired melanoma cell migration and invasion." (PMID 36230699, 2022). "Altogether, these data indicate that targeting both SMO and BRD4 drastically reduces the ability of melanoma-spheres to self-renew in vitro, supporting their efficacy against melanoma CSCs." (PMID 33958721, 2021). "To investigate the efficacy of the combined blockade of SMO and BRD4 in vivo, we assessed the effects of the drug combination in the growth of orthotopic A375 melanoma xenografts." (PMID 33958721, 2021). "In vitro studies on SMO and BRAF V600E kinase activity and in BRAF V600E A-375 human melanoma cell lines were further performed to examine their effects on these proteins and cancer cell lines and to corroborate computational predictions." (PMID 32380762, 2020). "Our findings in the WM278 cell line suggest that, in melanoma harboring amplification of GLI2, hedgehog target genes are constitutively transcribed and upstream inhibition of hedgehog signaling via SMO inhibitors is ineffective." (PMID 24287465, 2013). "SMO inhibition using siRNA and the small molecule inhibitor, NVP-LDE-225, suppressed melanoma growth in vitro, particularly in those cell lines with moderate SMO and GLI2 expression." (PMID 24287465, 2013). "Most recently, the SMO antagonist NVP-LDE-225, (Novartis Pharma, AG, Basel, Switzerland) has been shown to inhibit melanoma growth both in vitro and in vivo." (PMID 24287465, 2013). "However, we found out that silencing SMO and GLI1 resulted in decreased migration and invasiveness in melanoma under hypoxia." (PMID 36230699, 2022). "To test whether a similar interaction is present in melanoma cells, we next determined whether CAXII expression was affected by SMO or GLI1 in both the SK-MEL-28 and A375 cell lines." (PMID 36230699, 2022). "In conclusion, in this study we provide evidence of a novel mechanism of non-canonical SMO-independent activation of GLI1 by the SOX2-BRD4 axis and describe the efficacy of a combinatorial treatment with a novel SMO inhibitor and the PROTAC-derived BRD4 degrader MZ1 in melanoma." (PMID 33958721, 2021). "Here, we identify a novel SOX2-BRD4 transcriptional complex driving the expression of GLI1, the final effector of the HH/GLI pathway, providing a novel mechanism of non-canonical SMO-independent activation of HH/GLI signaling in melanoma." (PMID 33958721, 2021). "As the structures between SMO and FZD are similar, a possibility arises that itraconazole may target both Hh and Wnt signaling pathways in melanoma." (PMID 28212537, 2017).
melanoma (continued). "We also demonstrate that NVP-LDE-225, a small molecule SMO inhibitor already in clinical trials in other solid tumors, inhibits the hedgehog pathway effectively and has antitumor activity against B-RAF mutant melanoma both in vitro and in vivo." (PMID 24287465, 2013). "The remaining five receptors (DRD2, FZD4, GPR143, GPR161, and SMO) may be of interest in the context of melanoma, but they have not been studied yet." (PMID 35158973, 2022). "Thus, we tested whether combined inhibition of SMO and blockade of BRD4 may synergize in reducing self-renewal ability of melanoma CSCs." (PMID 33958721, 2021). "Since SMO has similar structure with FZD, an upstream modulator of Wnt/β-catenin signaling pathway, which raises a question whether the FZD-Wnt pathway is also involved in the anti-melanoma effects of itraconazole." (PMID 28212537, 2017). "Indeed, our data showed that chemical targeting of SMO and GLI1 can impair CAXII expression and melanoma migration and invasion, highlighting, in this experimental model, the possibility to develop small molecules that are more effective in reducing melanoma aggressiveness." (PMID 38399442, 2024). "Therefore, we decided to test these Hh inhibitors in vitro in order to target SMO and/or GLI1 and analyse melanoma migration and invasion to see if they could reduce this activity as a first step in developing new therapeutical strategies for melanoma treatment." (PMID 38399442, 2024). "In melanoma cells, SOX2 activates GLI1 in a non-canonical SMO-independent way by binding to the CTTGGATT sequence at -423 bp upstream of the TSS and activating GLI1 expression." (PMID 37149646, 2023). "In conclusion, the response to GANT61, a GLI inhibitor, compared to the poor response to cyclopamine, a SMO inhibitor, supports non-canonical HH-GLI pathway activation in melanoma cell lines." (PMID 36139698, 2022). "In addition, several types of cancer, including melanoma, present non-canonical activation of the GLI transcription factors through multiple oncogenic inputs independent of upstream PTCH/SMO signaling." (PMID 39998753, 2025). "Although MRT-92 appears a promising candidate for future clinical studies, interference with SMO alone may not be effective in blocking HH signaling in cancers having canonical and non-canonical HH/GLI signaling activation, such as melanoma." (PMID 33958721, 2021).